BDNF (brain derived neurotrophic factor)
Diseases named in the same sentence as BDNF in open-access papers (continued):
Sharing a sentence is not in itself a finding about the gene and the disease.
colitis (38 papers, 2012 to 2026). Inflammation of the colon. "Studies have shown that experimental colitis and intestinal dysbiosis are associated with aberrant mRNA or protein expression of brain-derived neurotrophic factor in the HIPP/paraHIPP and the abnormal development of anxiety-like behavior." (PMID 29212177, 2017). "In the spinal cord, colitis caused an increase in the level of NR1 Ser896 phosphorylation which was attenuated by inhibition of endogenous BDNF action with a specific BDNF antibody." (PMID 26289587, 2015). "The present study explores the molecular mechanisms and pathways that underlie the BDNF action in the spinal cord during colitis." (PMID 26289587, 2015). "Intrathecal infusion of BDNF neutralizing antibody via mini pump also attenuates colitis-associated bladder hyperactivity." (PMID 26289587, 2015). "Furthermore, TNBS-induced colon inflammation is associated with high BDNF expression and the stimulation of sensory neurons in the dorsal root ganglia." (PMID 36225193, 2022). "However, in rats with high estrogen at the time of testing (proestrus), experimental colitis caused a significant up-regulation of BDNF colonic content from 26.1±8.5 pg/ml to 83.4±32.5 pg/ml (3.2-fold increase, N = 7, p≤0.05 to respective control)." (PMID 24788240, 2014). "Priming exposure related to GluN1 subunit activation was reported in describing activation of BDNF as a contributor to colitis hypersensitivity, but low levels of BDNF provide protection from excitotoxicity." (PMID 37686003, 2023). "Treatment with liver hydrolysate rescued neuroinflammation and depressive-like behavior in acute DSS-induced colitis, putatively by inducing BDNF expression via adenosine monophosphate-activated protein kinase (AMPK)." (PMID 36232412, 2022). "Limited studies in models of chemically-induced colitis provide evidence that BDNF expression is reduced in the hippocampus (DNBS) and forebrain (DSS) with IL-1β expression elevated in DSS models." (PMID 34983592, 2022). "In contrast, treatment of rat colon smooth muscle tissue with TNF-α and IL-1β resulted in a significant increase in the protein expression of BDNF, suggesting that colitis elevates BDNF levels inside the colon wall." (PMID 35274002, 2022). "MicroRNA profiling showed a total of 56 miRNAs significantly increased in the heart by colitis, 8 of which are predicted to target brain-derived neurotrophic factor (BDNF)." (PMID 34543287, 2021). "We utilized microarray analysis to identify the rat miRNAs significantly modulated by DSS colitis, and isolated the mRNAs predicted to target BDNF." (PMID 34543287, 2021). "In order to validate the changes induced by DSS, we also assessed BDNF expression in TNBS-induced acute colitis in adult rats, another well characterized rodent model of colitis." (PMID 34543287, 2021). "Three miRNAs, miRNA-155, Let-7, and miR-1, were significantly increased in DSS colitis, and their common target, BDNF, was decreased significantly in cells transfected with the miRNA of interest." (PMID 34543287, 2021). "Heterozygous BDNF+/- mice developed lower colonic nociception under both control conditions and after trinitrobenzesulfonic acid-induced colitis." (PMID 30794676, 2019). "The present study also reveals that BDNF- and colitis-induced NR1 phosphorylation at Ser896 is regulated by the PI3K/Akt pathway." (PMID 26289587, 2015). "In both L1 and S1 spinal cord, neutralization of BDNF action in vivo with specific BDNF antibody reversed colitis-induced NR1 phosphorylation." (PMID 26289587, 2015). "During colitis, the level of BDNF was elevated in the DRG, specifically in the colonic afferent neurons." (PMID 26289587, 2015). "In the present study, the PI3K/Akt pathway also mediates BDNF- and colitis-induced NR1 phosphorylation at Ser896 in the spinal cord." (PMID 26289587, 2015). "The PI3K/Akt pathway, in addition to PLCγ and PKC, mediates BDNF action in the spinal cord during colitis." (PMID 26289587, 2015).
colitis (continued). "In particular with colitis, systemic injection of BDNF neutralizing antibody reverses colonic hypersensitivity in response to colonic distention." (PMID 26289587, 2015). "BDNF participates in colitis-induced spinal central sensitization by up-regulating NR1 phosphorylation at Ser896." (PMID 26289587, 2015). "In the current work we found that hippocampal BDNF expression was significantly diminished in mice with DSS-induced colitis." (PMID 25414650, 2014). "In terms of bladder hyperactivity, we recently showed that intrathecal sequestration of BDNF action reduced colitis-induced bladder hyperactivity suggesting the role of BDNF in the regulation of bladder function." (PMID 24303055, 2013). "Our recent study in a colitis-induced visceral pain model shows that BDNF is largely co-expressed with the transient receptor potential cation channel TRPV1, suggesting a role of BDNF in nociception." (PMID 24303055, 2013). "A recent study has shown that with colitis BDNF(+/-) mice exhibit weaker visceral responses to colorectal distension and lower sensitivity in the colon than BDNF(+/+) mice." (PMID 22335898, 2012). "BDNF antibody treatment also reversed the reduction in the quantity of urine per voiding during colonic inflammation." (PMID 22335898, 2012). "Systemic knockdown of BDNF activity by intraperitoneal injection of BDNF neutralizing antibody also reverses colitis-induced colonic hypersensitivity." (PMID 22335898, 2012). "Similarly, in rats with colitis induced using dextran sodium sulfate, the expression of BDNF in longitudinal smooth muscle cells was higher compared to controls." (PMID 36984890, 2023). "Neuroinflammation and suppression of hippocampal neurogenesis in models of colitis could be due to impairments in the AMPK/BDNF signalling pathway." (PMID 34983592, 2022). "Our data suggest that chronic colitis impedes heart function, at least partially, by elevating exosomal miR-29b to disrupt BDNF signaling and that BDNF agonists might offer therapeutic and preventive benefit to the patients with IBD." (PMID 35274002, 2022). "Moreover, up-regulation of CTGF and BDNF was also prevented in sites P and I. Treatment with clear liquid diet markedly improved inflammation, fibrosis, and muscle hyperplasia in the colitis rats." (PMID 34992543, 2021). "Interestingly, a total of 8 miRNAs increased by colitis in microRNA microarrays were predicted as regulators of BDNF." (PMID 34543287, 2021). "We demonstrated that in response to chronic colitis, both serum and heart BDNF levels were significantly downregulated, which could adversely influence heart function." (PMID 34543287, 2021). "DSS induced colitis also suppressed BDNF mRNA expression in the adult heart (30%, p<0.05)." (PMID 34543287, 2021). "(iv) DSS-induced colitis was associated with an increase in circulating IL6, IL18, and NPY, an increased expression of COX-2 mRNA in the hypothalamus, and a decreased expression of BDNF, NPY, and MR mRNA in the hippocampus." (PMID 25414650, 2014). "Experimental colitis had similar effects on the level of BDNF in the urinary bladder which was also up-regulated by 5-fold in rats in proestrus (from 8.4±3.9 pg/ml to 43.8±15.6 pg/ml, p≤0.05 to control) but not in diestrus when compared with respective control groups." (PMID 24788240, 2014). "BDNF level is found to increase in primary afferent neurons in several models of inflammatory and neuropathic pain such as formalin and carrageenan-induced peripheral pain models or colitis-induced visceral pain." (PMID 24303055, 2013). "The role of BDNF in mediating sensory sensitization is also observed in other systems including colitis-induced visceral hypersensitivity in response to colonic distention, peripheral inflammation-induced somatic pain, cancer-induced bone pain, and a variety of other systems." (PMID 24303055, 2013). "Yet, whether and how cardiac BDNF is repressed by colitis remain to be determined." (PMID 35274002, 2022).
colitis (continued). "Importantly, DSS colitis markedly decreased BDNF in both myocardium and serum." (PMID 34543287, 2021). "In addition, BDNF released from dorsal root ganglia and spinal cord contributed to the development of exaggerated visceromotor responses to colorectal distension in a rat model of colitis." (PMID 30794676, 2019). "DSS-induced colitis was associated with an increase in circulating neuropeptide Y (NPY), a rise in the hypothalamic expression of cyclooxygenase-2 mRNA and a decrease in the hippocampal expression of NPY mRNA, brain-derived neurotrophic factor mRNA and mineralocorticoid receptor mRNA." (PMID 25414650, 2014). "A recent study found that in a rat model of colitis, the activation of ERK5 mediated BDNF upregulation in the DRG primary afferent neurons." (PMID 36910013, 2023). "In line with this, BDNF levels in the brain were reduced in acute and chronic DSS-induced as well as in DNBS-induced colitis." (PMID 36232412, 2022). "Apart from the increase in colonic BDNF expression, the expression of BDNF in the spinal cord and DRG is high in colitis (Qiao, Gulick, Bowers, Kuemmerle, & Grider, 2008)." (PMID 31976585, 2020). "Recent animal studies with systemic drug intervention by injecting antiserum of either NGF or BDNF to rats with colitis suggested a possible interaction of the NGF and BDNF pathways in colitis-induced visceral hypersensitivity." (PMID 24788240, 2014). "Our previous studies showed that the BDNF mRNA level was increased in the L1 and S1 DRG at 3 days of colitis." (PMID 22335898, 2012). "To examine the phenotype of BDNF immunoreactive neurons in the DRG in order to validate a role of BDNF in sensory plasticity, we performed double immunostaining of BDNF and the nociceptive marker TRPV1 in the L1 DRG at 3 days of colitis." (PMID 22335898, 2012). "In vivo, mice with DSS-induced colitis presented with brain region-specific alterations in HPA axis-related peptides, glucocorticoid receptor gene expression, and factors including NPY, NPY receptor Y1, CRF, CRF receptor 1, and BDNF." (PMID 34983592, 2022). "BDNF protein levels in the serum and mRNA expression in the heart were significantly reduced by TNBS-induced colitis compared to controls (95% and 33%, respectively, p<0.05), confirming that both acute and chronic inflammation in the colon suppresses BDNF levels in the heart." (PMID 34543287, 2021). "During colitis, the level of NR1 phospho-Ser896 was increased in the dorsal horn region of the L1 and S1 spinal cord; this increase was attenuated by injection of BDNF neutralizing antibody to colitic animals (36 μg/kg, intravenous (i.v.)) and was also reduced in BDNF+/− rat treated with TNBS." (PMID 26289587, 2015). "Among these three pathways, MEK/ERK pathway is activated by BDNF in the spinal cord during colitis; however, it is not involved in BDNF-induced NR1 phosphorylation at Ser896 characterized in the present study." (PMID 26289587, 2015). "Even though the ERK pathway was also activated in the spinal cord by BDNF during colitis, the activation of this pathway did not lead to NR1 phosphorylation at Ser896." (PMID 26289587, 2015). "In DRG culture, BDNF also increases the expression level of CGRP, an excitatory neurotransmitter that is up-regulated in bladder afferent neurons during colonic inflammation, suggesting a possible complimentary role of BDNF in modulating CGRP expression and associated bladder afferent excitability." (PMID 24788240, 2014). "In DRG neuron culture, BDNF increases the expression level of CGRP, an excitatory neurotransmitter that is also up-regulated in the bladder afferent neurons during colonic inflammation, suggesting a possible role of BDNF in modulating bladder afferent excitability." (PMID 22335898, 2012). "Interestingly, expression of CTGF and BDNF was not significantly upregulated in the non-distended site D, suggesting that expression of CTGF and BDNF expression is stretch-sensitive in the CD-like colitis model." (PMID 34992543, 2021).
atherosclerosis (37 papers, 2008 to 2025). A disease characterized by the build-up of fatty material and calcium deposition in the arterial wall resulting in partial or complete occlusion of the arterial lumen. "While numerous studies have established associations between brain-derived neurotrophic factor (BDNF) and cognitive functioning, limited research has delved into the role of BDNF concerning cognitive outcomes in atherosclerosis-related conditions." (PMID 39619329, 2024). "Recent studies reveal that BDNF is associated with systemic inflammation that occurred in DM, atherosclerosis, and acute coronary syndrome, and atherosclerosis." (PMID 36787304, 2023). "BDNF levels were linked to an increase of 80 EV-derived miRNAs and a decrease of 59 miRNAs related to atherosclerosis and thrombosis." (PMID 35911513, 2022). "Recent data suggest new potential risk factors for atherosclerosis and platelet aggregation such as adiponectin, BDNF, sCD40L, TIMP1, serpin E1/PAI I, and VEGF." (PMID 33020432, 2020). "Here we show an age-related increase of BDNF level DS patients serum, thus indicating a protective role of this molecule against atherosclerosis risk as observed by Nelson at al, showing that BDNF increase with age in healthy subject." (PMID 20181009, 2010). "Decreased BDNF in the blood may cause endothelial and vascular dysfunction and atherosclerosis due to increased oxidative stress and inflammation." (PMID 38137853, 2023). "Therefore, the BDNF/TrkB pathway plays a protective role in atherosclerosis and pathway deficiency has been proven to accelerated development of atherosclerotic lesions in ApoE−/− mice." (PMID 34206655, 2021). "Recent data also suggest new potential risk factors for atherosclerosis and platelet aggregation such as brain-derived neurotrophic factor (BDNF), sCD40L (soluble CD40 ligand), serpin E1/PAI I (endothelial plasminogen activator inhibitor), and vascular endothelial growth factor (VEGF)." (PMID 33020432, 2020). "Lower BDNF level was connected with an increased risk of cardiovascular diseases, and this may indicate pathogenetic association between BDNF and atherosclerosis and endothelial dysfunction." (PMID 33343231, 2020). "Decreased serum concentrations of BDNF have been observed in patients affected by atherosclerosis, suggesting a potential link between BDNF levels and the condition." (PMID 39619329, 2024). "A low circulating BDNF concentration was reported to significantly predict the incidence of CKD in the Hyogo Sleep Cardio-Autonomic Atherosclerosis Study." (PMID 35800175, 2022). "A lower circulating BDNF level significantly predicted the development of CKD in Japanese individuals in the Hyogo Sleep Cardio-Autonomic Atherosclerosis Study." (PMID 35800175, 2022). "Patients with DMAS (Diabetes Mellitus Accelerated Atherosclerosis) had a lower expression of BDNF, and it was negatively correlated with inflammation." (PMID 34885795, 2021). "In mice BDNF decreases VE-cadherin cleavage to reduce atherosclerosis and promotes vascular integrity through Ets1-mediated VE-cadherin expression." (PMID 31659205, 2019). "In the present study, we examined the relationship between plasma BDNF concentration and future development of CKD in patients with cardiovascular risk factors as part of the Hyogo Sleep Cardio-Autonomic Atherosclerosis (HSCAA) cohort study." (PMID 28575038, 2017). "Furthermore, altered BDNF levels are involved in endothelial cell dysfunction, a key early process in atherosclerosis development." (PMID 38137853, 2023). "Surprisingly, BDNF is crucial not only for the central nervous system but also for atherosclerosis." (PMID 34885795, 2021). "In the present study, we found BDNF elevation suggesting that high levels of circulating BDNF could protect DS patients from the clinical complications of atherosclerosis." (PMID 32280719, 2020).
atherosclerosis (continued). "In summary, our results support the conclusion that these proteins (i.e., SPP1, ATP6V0D2, CHI3L1, and BDNF) likely play important roles in the development of atherosclerosis-related diseases and further indicate that they are potential diagnostic and therapeutic biomarkers." (PMID 31682178, 2019). "Furthermore, our study indicates that SPP1, CD36, ATP6V0D2, CHI3L1, MYH11, and BDNF, which showed favorable diagnostic performance and high correlations with several clinical biochemical parameters, may potentially serve as biomarkers to diagnose and monitor the prognosis of atherosclerosis." (PMID 31682178, 2019). "Therefore, our data revealed that the endothelial BDNF-TrkB pathway is a novel growth factor signal for protecting against atherosclerosis." (PMID 26431274, 2015). "High levels of circulating BDNF may protect DS patients from the clinical complications of atherosclerosis." (PMID 20181009, 2010). "Aging is a relevant factor affecting BDNF's ability to protect neuronal activity, but age related effects on BDNF function in non neuronal cells, in particular in atherosclerosis, still remain unclear." (PMID 20181009, 2010). "we suggest that in DS patients, elevated peripheral BDNF may protect against atherosclerosis, in particular in old DS people." (PMID 20181009, 2010). "BDNF might be a protective biomarker for the clinical manifestation of atherosclerosis in DS." (PMID 20181009, 2010). "Our study highlighted the therapeutic effects of sulforaphane on AD by regulating the apoptosis signaling pathway, the “brain-derived neurotrophic factor (BDNF) signaling pathway”, “lipid and atherosclerosis”, and the “AGE-RAGE signaling pathway in diabetic complications”." (PMID 39493676, 2024). "The reasons remain unclear, but recent studies have reported the potential importance of neurotrophins, such as nerve growth factor (NGF) and brain-derived neurotrophic factor (BDNF), in atherosclerosis and related disorders." (PMID 20181009, 2010).